IL6 (interleukin 6)
Diseases named in the same sentence as IL6 in open-access papers (continued):
Sharing a sentence is not in itself a finding about the gene and the disease.
myxoma (continued). "Immunohistochemical staining and reverse transcription-polymerase chain reaction (RT-PCR) revealed that IL-6 and its receptors, IL-6 receptor (IL-6R) and gp130, co-existed in the myxoma cells." (PMID 38396907, 2024). "RT-PCR with specific primers demonstrated that both myxoma cells and HUVECs yielded positive products for IL-6, and its receptor complexes, IL-6R and gp130." (PMID 38396907, 2024). "To further confirm the role of STAT3 in the secretion of IL-6, we transfected antibody-free myxoma cells with STAT3 siRNA." (PMID 38396907, 2024). "The present study also demonstrated that STAT3 was constitutively phosphorylated together with spontaneous secretion of IL-6 in the cultured myxoma cells." (PMID 38396907, 2024). "The cultured myxoma cells were exposed to IL-6 + sIL-6R for different time periods (5 to 120 min), and their protein extracts were examined by Western immunoblot analysis." (PMID 38396907, 2024). "Cultured myxoma cells spontaneously secreted considerable amounts of IL-6 into the culture medium from 8 to 24 h." (PMID 38396907, 2024). "Several factors, like family history of myxoma, young age, multifocal tumors, and interleukin-6, play a significant role in the recurrence of myxoma." (PMID 37151857, 2023). "Elevated IL-6 levels have been detected in patients with myxomatous aneurysms, before and even after myxoma resection." (PMID 36675669, 2022). "Based on this theory, cardiac myxoma resection is usually accompanied by a reduction in serum IL-6 levels, but a few studies have shown new aneurysm formation after the myxoma resection still showed persistently elevated IL-6 levels." (PMID 36675669, 2022). "Recent studies suggest that autocrine production of IL-6 by myxoma plays a main role in the embolization of the myxomatous cell." (PMID 36675669, 2022). "Myxoma cells produce and release proinflammatory cytokine interleukin-6 (IL-6), which is an important factor of aneurysm initiation." (PMID 36675669, 2022). "It is common for heart tumors to increase the levels of proinflammatory cytokines (interleukin 6, especially in myxoma)." (PMID 32751243, 2020). "Constitutional symptoms include raised inflammatory markers with fever, weight loss, or symptoms resembling connective tissue disease due to cytokine (interleukin-6) secretion by the myxoma itself, infection, or malignancy." (PMID 25480676, 2014). "Myxomas produce a vascular endothelial growth factor that stimulates angiogenesis and tumor growth and an increased expression of interleukin-6." (PMID 18706121, 2008). "IL-6 concentrations in the supernatant of myxoma cells increased in a time-dependent manner." (PMID 38396907, 2024). "In addition, the RT-PCR study showed the expressions of IL-6 mRNA, IL-6R mRNA, and gp130 mRNA in the myxoma cells, together with calretinin mRNA." (PMID 38396907, 2024). "Therefore, we analyzed the gene expression of IL-6 mRNA to investigate the role of IL-6 on the myxoma cells." (PMID 38396907, 2024). "Therefore, it seems likely that circulating IL-6 in patients with cardiac myxoma is derived from the neoplastic myxoma cells." (PMID 38396907, 2024). "Although the precise causative and functional roles of these factors in the cardiac myxoma cells remain unknown, IL-6 and these substances have an important role in inflammation, tumor growth, angiogenesis, and tumor cell migration in the cardiac myxomas." (PMID 38396907, 2024). "Thus, we analyzed trans-signaling by using IL-6 + sIL-6R for activation of IL-6 mRNA and found that IL-6 trans-signaling caused autocrine activation of IL-6 gene expression through STAT3 and PI3K/Akt pathways in the myxoma cells." (PMID 38396907, 2024). "Elevated levels of interleukin-6 (IL-6), vascular endothelial growth factor (VEGF), basic fibroblast growth factor (bFGF), and monocyte chemotactic protein-1 (MCP-1) have been implicated in the pathogenesis of myxomas." (PMID 37197119, 2023).
myxoma (continued). "Two possible risk factors for developing myxomas (VEGF and IL-6) are explored and discussed." (PMID 35016713, 2022). "Real-time PCR demonstrated that IL-6 + sIL-6R-induced increase in IL-6 mRNA was significantly suppressed by the pretreatment with JAK-STAT inhibitors, such as AG490, piceatannol, and LLL12 in the myxoma cells." (PMID 38396907, 2024). "In the present study, stimulation with IL-6 + sIL-6R resulted in an increase in IL-6 mRNA, and pharmacological inhibitors against JAK/STAT3 and PI3L/Akt inhibited the IL-6 + sIL-6R-induced activation of IL-6 mRNA in the myxoma cells." (PMID 38396907, 2024). "But it’s not clear how often IL-6-mediated systemic inflammation in myxoma can be mistaken for autoimmune flares." (PMID 41552135, 2025). "The higher IL-6 and CRP levels inpatients with sessile cardiac myxoma might implicate that more cells or exposedendothelium might remain in the large sessile myxomas." (PMID 30810670, 2019). "As no recurrentcardiac myxoma case was included in the present patient cohort, the predictive valueof IL-6 in tumor recurrence was not evaluated." (PMID 30810670, 2019). "In addition to IL-6, monocyte chemoattractant protein (MCP)-1, granulocyte-macrophage colony-stimulating factor (GM-CSF), and platelet-derived growth factor (PDGF)-BB were also increased in the supernatant of the cultured myxoma cells." (PMID 38396907, 2024). "We and other investigators reported that IL-6 induced MCP-1 in human vascular endothelial cells and peripheral mononuclear cells, suggesting the possibility that IL-6 secreted from the cardiac myxoma cells stimulates MCP-1 production in the myxoma cells or various other cells around." (PMID 38396907, 2024). "IL-6 and CRP levelsdid not differ between patients with a cardiac myxoma of irregularappearance and those with a myxoma of regular gross appearance, or betweenpatients with a pedicled or a sessile myxoma." (PMID 30810670, 2019).
spinal cord injury (25 papers, 2012 to 2025). Penetrating and non-penetrating injuries to the spinal cord resulting from traumatic external forces (e.g., WOUNDS, GUNSHOT; WHIPLASH INJURIES; etc.). "There are studies showing that passive heating of the organism can cause a sharp increase in circulating IL-6 levels in young, healthy men, in overweight young men, and in men with a spinal cord injury." (PMID 36552653, 2022). "Previous studies indicated that in spinal cord injuries, M1 macrophages facilitate phagocytosis and secrete pro-inflammatory cytokines such as interleukin-6 (IL-6) and tumor necrosis factor alpha (TNF-α)." (PMID 38668224, 2024). "At rest, the concentration of IL-6 was significantly higher in individuals with cervical spinal cord injuries (2.18 ± 0.44 pg/mL versus 1.02 ± 0.22 pg/mL, p-value < 0.05)." (PMID 37372810, 2023). "Spinal Cord Injury patients, on average 28 years after injury, displayed a 525% increase in IL-6, 115.9% increase in circulating vascular adhesion molecule (sVCAM)-1, and 44.4%increase in endothelin-1." (PMID 34220440, 2021). "Spinal Cord Injury is associated with increased pro-inflammatory cytokine expression in the brain, such as TNF-α, IL-6, and IL-1β, which have potential to reduce adult hippocampal neurogenesis." (PMID 34220440, 2021). "Studies have found that miR-223 and the inflammatory factors TNF-α, IL-1β, and IL-6 were highly expressed in the lesions of acute spinal cord injury in mice, which reached the maximum peak at 12–24 h after injury." (PMID 32295141, 2020). "IL-6 is established to play a key role in astrogliosis and recovery of function in the context of spinal cord injury (SCI)." (PMID 28700615, 2017). "Based on the principle of antigen-antibody specific binding, an electrochemical sensor utilizing Prussian blue nanoparticles (PBNPs) was developed to detect the expression of the inflammatory cytokine interleukin-6 (IL-6) in vivo following spinal cord injury (SCI)." (PMID 41323701, 2025). "Further mechanisms with relevance for neurologic disorders are the downregulation of matrix metalloproteinase-2 (MMP-2), MMP-9 and interleukin (IL-6) which, in an animal experiment of spinal cord injury (SCI), inversely correlated with the spinal water content, thus promoting recovery." (PMID 40731157, 2025). "Our previous study demonstrated that M1 macrophages could impair tight junctions (TJs) between vascular endothelial cells by secreting interleukin-6 (IL-6) after spinal cord injury (SCI)." (PMID 36624478, 2023). "For instance, it has been found that electroacupuncture reduced the proportion of M1 macrophages and the levels of TNF-α, IL-1 β, and IL-6 in rats with spinal cord injury and also increased the amount of IL-10 and M2 macrophages and upregulated the expression of the M2 markers CD206 and NT-3." (PMID 33727948, 2021). "In the spinal cord injury (SCI) model, IL-6-induced activation of the JAK2/STAT3 signaling pathway in spinal dorsal horn microglia and astrocytes contributes to the progression of pain." (PMID 40093024, 2025). "In a previous study, rats with spinal cord injuries received (DP) therapy, which markedly decreased their levels of TNF-α and IL-6 activity." (PMID 36641447, 2023). "For instance, an animal model of spinal cord injury (SCI), EA has shown neuroprotective effects by reducing levels of microglial and proinflammatory mediators, such as precursor pro-nerve growth factor and proinflammatory cytokines (TNF-α, IL-1β, and IL-6)." (PMID 32283868, 2020). "Another study demonstrated that Tan IIA could reduce the levels of IL-6, TNF-α and IL-1β by markedly inhibiting the activation of NF-κB and the mitogen-activated protein kinases (MAPKs) pathways in a spinal cord injury model." (PMID 25157742, 2014). "The lack of exercise-related IL-6 response in individuals with cervical spinal cord injuries could be due to muscle atrophy and sympathetic nervous system dysfunction." (PMID 37372810, 2023).
spinal cord injury (continued). "For instance, Yang and colleagues demonstrated that a contused model of spinal cord injury (SCI) in mApoE-knockout mice led to an exaggerated inflammatory response with increased expression of nuclear factor κB (NF-κB) and cytokine levels such as IL-6 and IL-1β." (PMID 34369386, 2021). "The objective of this study was to clarify the effects of a temporal blockade of IL-6/IL-6 receptor (IL-6R) engagement, using an anti-mouse IL-6R monoclonal antibody (MR16-1), on macrophage activation and the inflammatory response in the acute phase after spinal cord injury (SCI) in mice." (PMID 22369693, 2012). "Individuals with spinal cord injury (SCI) are prone to develop metabolic diseases due to the lack of exercise-related IL-6 response, suggesting that IL-6 plays a pivotal role in regulating glucose homeostasis." (PMID 30761018, 2019).
TAFRO syndrome (25 papers, 2014 to 2025). "In contrast, other forms of iMCD-NOS, as well as iMCD-TAFRO and TAFRO syndrome, likely involve a more intricate interplay of pathogenic factors that extend beyond IL-6." (PMID 38927348, 2024). "Although the pathogenesis of the kidneys’ involvement in TAFRO syndrome is not clearly understood, cytokine storms involving IL-6 and VEGF have been suggested to cause immunological disorders and vascular endothelial cell damage." (PMID 38672203, 2024). "IL-6 inhibitors, while important in iMCD treatment, have shown variable efficacy in TAFRO syndrome, implying that alternative or additional pathogenic pathways are at work and warrant further investigation." (PMID 38927348, 2024). "Based on these findings, we diagnosed acute exacerbation of IP associated with TAFRO syndrome due to IL-6 overproduction-associated cytokine storm." (PMID 37746092, 2023). "Although some findings are different between idiopathic multicentric Castleman’s disease (not otherwise specified) and TAFRO syndrome, cytokines play an important role in both subtypes, as TAFRO syndrome is often associated with high IL-6 and vascular endothelial growth factor (VEGF) levels." (PMID 38872134, 2024). "Fourth, hypercytokinemia, including elevated IL-6 caused by TAFRO syndrome, could also have contributed to this unusual situation." (PMID 33402219, 2021). "It is thought that the pathogenesis of TAFRO syndrome might be associated with a strong hypercytokine storm, including IL-6 and VEGF." (PMID 24890946, 2014). "While the pathophysiology of iMCD and TAFRO syndrome remains not fully understood, the proinflammatory cytokine interleukin-6 (IL-6) is both a central driver of disease pathogenesis and a key therapeutic target." (PMID 40248702, 2025). "In contrast, iMCD-TAFRO and TAFRO syndrome frequently respond poorly to IL-6 inhibitors and have an acute-to-subacute course." (PMID 38927348, 2024). "Although IL-6 is strongly associated with the symptomatology and progression of the IPL subtype of iMCD, its role in TAFRO syndrome pathogenesis is less clear." (PMID 38927348, 2024). "The common consensus suggests that overproduction of IL-6, alongside other factors, plays a pivotal role in the pathogenesis of both iMCD and TAFRO syndrome." (PMID 38927348, 2024). "IL-6, VEGF, and platelet-associated IgG are often elevated in TAFRO syndrome, as in this case, suggesting the possibility of a combined MIS-A, SCLS, and ITP lesion." (PMID 38872134, 2024). "The usefulness of tocilizumab is based on the observation of elevated serum interleukin (IL)-6 levels in patients with TAFRO syndrome." (PMID 36805700, 2023). "In TAFRO syndrome, elevated levels of cytokines, including interleukin-6 (IL-6) and vascular endothelial growth factor (VEGF), are thought to induce inflammation and vascular permeability, leading to organ damage." (PMID 35870879, 2022). "The clinical response of targeted therapy for TAFRO syndrome is also closely related to serum IL-6 and CRP concentrations." (PMID 34208103, 2021). "We suspect that VEGF and IL-6 play a key role in the physiopathology of the spectrum of renal involvement from TMA-like to MPGN observed in TAFRO syndrome." (PMID 31316523, 2019). "Additional work-up for TAFRO syndrome included an elevated IL-2R of 8944 (reference range 622–1619 pg/mL), IL-6 596 (reference range 0.31–5 pg/mL), and CRP 30 (reference range 0–10 mg/ml)." (PMID 27777802, 2016). "Upon the diagnosis of TAFRO syndrome, the patient was initially started on sole anti-IL-6 therapy with tocilizumab, 8 mg/kg every 2 weeks." (PMID 27777802, 2016). "While both illnesses include high levels of interleukin-6 (IL-6), TAFRO syndrome has more dramatic increases in a broader spectrum of cytokines, including vascular endothelial growth factor (VEGF) and C-reactive protein (CRP), which contribute to its aggressive clinical presentation." (PMID 39398672, 2024).
TAFRO syndrome (continued). "Here in our case, the IL-6 level was normal, implicating cytokines other than IL-6 may play an important role in the pathophysiology of the iMCD-TAFRO syndrome." (PMID 39093747, 2024). "It has been hypothesized that the pathogenesis of TAFRO syndrome involves an increase in inflammatory cytokines, such as IL-6 and vascular endothelial growth factor (VEGF)." (PMID 38672203, 2024). "Elevated serum IL-6 levels, however, are still frequently found in patients with TAFRO syndrome." (PMID 34208103, 2021). "The role of IL-6 in patients with TAFRO syndrome is not well known." (PMID 34208103, 2021). "More research is needed to elucidate the roles that VEGF and IL-6 might be playing in the renal involvement identified in TAFRO syndrome." (PMID 31316523, 2019). "Tocilizumab (TCZ) could be used safely in patients with renal impairment, and it might be a reasonable choice considering that excessive IL-6 secretion is one of the main pathophysiological events in TAFRO syndrome." (PMID 34171004, 2018). "Considering the mechanism of action of CsA, IL-2 may play a pivotal role in TAFRO syndrome in addition to IL-6." (PMID 34171004, 2018). "However, the role of IL-6 in TAFRO syndrome is more complex." (PMID 38927348, 2024). "The increased levels of serum IL-6 and VEGF could increase permeability of the arteriolar wall and glomerular capillaries and could be associated with endothelial injuries in patients with TAFRO syndrome." (PMID 34171004, 2018). "Due to similarity in histopathologic features and elevated expression of IL-6 in patients with MCD and TAFRO syndrome, TAFRO syndrome was described as a related disorder to MCD." (PMID 35992883, 2022). "We suspect that there is a continuum between TMA and MPGN lesions in TAFRO syndrome favored by VEGF and IL-6." (PMID 31316523, 2019). "Although elevated levels of interleukin-6 (IL-6) and vascular endothelial cell growth factor (VEGF) are seen in the serum and effusions of patients with TAFRO syndrome, the pathogenesis of the disease remains obscure." (PMID 24890946, 2014). "We speculate that there is a continuum between TMA-like and MPGN renal lesions in TAFRO syndrome that may involve VEGF, PDGF-B, and IL-6 production." (PMID 31316523, 2019). "It is known that iMCD-NOS is mainly characterized by IPL-like plasma cell infiltration and anti-IL-6 antibodies are relatively effective, but it is thought that various factors other than IL-6 are involved in the cytokines and chemokines involved in iMCD-TAFRO and TAFRO syndrome." (PMID 39451548, 2024). "The standard of care has not been fully established, but interleukin-6 blockade therapy with siltuximab or tocilizumab and anti-inflammatory therapy with high-dose corticosteroids are the most commonly applied for the treatment of TAFRO syndrome." (PMID 38927484, 2024). "There are still unknown factors, on top of IL-6, that determine the presentation of non-TAFRO idiopathic MCD or TAFRO syndrome." (PMID 34208103, 2021).